NPY (neuropeptide Y)
Diseases named in the same sentence as NPY in open-access papers (continued):
Sharing a sentence is not in itself a finding about the gene and the disease.
vitiligo (10 papers, 2014 to 2025). Generalized well circumscribed patches of leukoderma that are generally distributed over symmetric body locations and is due to autoimmune destruction of melanocytes. "Gene association studies have identified polymorphisms in the NPY gene as a risk factor for vitiligo in multiple populations." (PMID 35418942, 2022). "Laddha and colleagues have associated single nucleotide polymorphisms (SNPs) in the promoter region (-399T/C; rs16147) and second exon (+1128T/C; rs16139) of NPY with increased susceptibility for vitiligo in Indian populations." (PMID 35418942, 2022). "There has been evidence to suggest genetic associations of NPY with vitiligo as well as evidence that shows differential expression of NPY in these and other skin pathologies." (PMID 35418942, 2022). "Along with genetic mutations that increase the susceptibility for vitiligo, increased NPY levels have been seen in the circulation of subsets of AD and vitiligo patients." (PMID 35418942, 2022). "Distribution of haplotypes frequencies for NPY gene structural and promoter polymorphisms (1128 T/C and −399 T/C) among vitiligo patients and controls." (PMID 25221996, 2014). "We found that Leu7Pro (exon 2 +1128 T/C) polymorphism as well as (−399 T/C) promoter polymorphism of NPY were significantly associated with vitiligo susceptibility." (PMID 25221996, 2014). "‘TC’ haplotype containing minor alleles of NPY polymorphisms was significantly higher in patients and increased the risk of vitiligo by 2.3 fold (p<0.0001)." (PMID 25221996, 2014). "In addition, there are increased allele frequencies for NPY − 399T/C (n = 454, p < 0.0001) and +1128T/C (n = 575, p < 0.0001) polymorphisms in vitiligo patients compared to controls (n = 1226, 1279, respectively)." (PMID 39861486, 2025). "Furthermore, NPY−399T/C (rs16147) and +1128T/C (rs16139) polymorphisms are correlated with vitiligo susceptibility and increase NPY transcription activity." (PMID 35721084, 2022). "Elevated level of NPY has been shown to be associated with vitiligo." (PMID 35721084, 2022). "Taken together, altered IL1B transcript levels due to genetic variability in IL1B might be associated with elevated NPY levels in patients with vitiligo." (PMID 25221996, 2014). "Neurotransmitters and neuropeptides associated with the sympathetic nervous system, including catecholamines, substance P, norepinephrine, and neuropeptide Y, have been found to be elevated in the skin or plasma of vitiligo patients." (PMID 39958821, 2025). "Neuropeptide Y (NPY), a neuropeptide linked to stress, is increased in vitiligo lesional and perilesional skin." (PMID 36902341, 2023). "Like other skin diseases, NPY has been found to be elevated in the lesional depigmented skin, as well as in the circulation, of vitiligo patients." (PMID 35418942, 2022). "Tu and colleagues showed that NPY is elevated from approximately 200 pmol in uninvolved skin to over 300 pmol in lesional skin from vitiligo patients." (PMID 35418942, 2022). "Candidate gene studies highlight the role of autoimmunity in vitiligo, as polymorphisms in IL1B, IL4, PSMB8, NLRP1, NPY, FOXP3, and IFNG genes were found to be associated with vitiligo." (PMID 36164321, 2022). "NPY, a 36 amino acid neuromodulator secreted by neurons, is believed to be involved in control of vitiligo development." (PMID 35721084, 2022). "Several studies have shown that the NPY levels of lesions and plasma in patients with vitiligo are significantly higher than in healthy volunteers." (PMID 35721084, 2022). "Tu and colleagues also showed that NPY is elevated in the plasma of vitiligo patients compared to that of healthy volunteers." (PMID 35418942, 2022). "Recently, we have reported the association of NPY and IL1B polymorphisms with vitiligo susceptibility in Gujarat population." (PMID 27749914, 2016).
vitiligo (continued). "Association studies for NPY gene exon 2 (+1128 T/C), promoter (−399 T/C) and IL1B gene promoter (−511 C/T) polymorphisms in Gujarat vitiligo patients and unaffected controls." (PMID 25221996, 2014). "Association studies for NPY gene exon 2 (+1128 T/C), promoter (−399 T/C) and IL1B gene promoter (−511 C/T) polymorphisms in generalized and localized vitiligo patients from Gujarat." (PMID 25221996, 2014). "The levels of NPY in the tissue fluids from skin lesions were significantly higher than those from unaffected skin in segmental vitiligo." (PMID 25221996, 2014). "Association studies for NPY gene exon 2 (+1128 T/C), promoter (−399 T/C) and IL1B gene promoter (−511 C/T) polymorphisms in active and stable vitiligo patients from Gujarat." (PMID 25221996, 2014). "The present study was designed to explore the role of NPY in vitiligo pathogenesis by addressing its non-synonymous (+1128 T/C) and promoter (−399 T/C) polymorphisms." (PMID 25221996, 2014). "Patients with local (p < 0.01) and segmental (p < 0.05) vitiligo types had higher NPY levels than controls, suggesting that NPY may be involved in the pathogenesis of specific vitiligo subtypes." (PMID 39861486, 2025). "Studies have shown changes in the number and distribution of skin nerve fibers in vitiligo patients, including those secreting neuropeptide Y (NPY) and calcitonin gene-related peptide (CGRP), as well as fibers reactive to the low-affinity nerve growth factor receptor (NGFr-IR)." (PMID 40508132, 2025). "Given that one of five receptors for NPY is present on immune cells, NPY might play a critical role in the pathogenesis of vitiligo via a neuro-immune mechanism involving melanocytes." (PMID 37255601, 2023). "Blocking NPY in these processes through therapeutic intervention could be promising in the treatment of AD, psoriasis, and vitiligo to enable improved qualities of life for those affected." (PMID 35418942, 2022). "Moreover, IL-1β can induce biosynthesis and release of NPY; in turn, NPY can be involved in the humoral immune mechanism leading to a higher level of IL-1β in vitiligo." (PMID 35721084, 2022). "Additionally, the level of NPY has been shown to be elevated in depigmented lesional skin of some vitiligo patients." (PMID 35418942, 2022). "The concentrations of NPY in skin fluids of vitiligo patients." (PMID 35418942, 2022). "Furthermore, Tu and colleagues quantified the concentration of NPY in tissue fluids isolated from lesional and uninvolved skin of vitiligo patients." (PMID 35418942, 2022). "Our results suggest that NPY −399T/C, +1128T/C and IL1B −511C/T polymorphisms are associated with vitiligo and IL1B −511C/T SNP influences its transcript levels leading to increased risk for vitiligo in Gujarat population." (PMID 25221996, 2014). "In order to understand the possible mechanism of action of NPY in vitiligo pathogenesis, neuro-immune-cutaneous system may be considered." (PMID 25221996, 2014). "Reactivity against NPY antibody was found to be higher in vitiligo patients in lesional and marginal areas during immunoreactivity studies with a neuronal marker suggesting that NPY may be involved in vitiligo pathogenesis." (PMID 25221996, 2014). "For example, inhibition of NPY signaling could mitigate vasoconstriction-induced hypoxia within the skin, which is one of the hypothesized mechanisms that contribute to melanocyte pathology during vitiligo." (PMID 35418942, 2022). "Although NPY has been shown to be elevated in the depigmented skin of vitiligo patients, it is not clear whether and how NPY contributes to melanocyte destruction during vitiligo pathogenesis and progression." (PMID 35418942, 2022). "Interestingly, they found that NPY is highest in patients with the generalized type of vitiligo, which could also be attributed to the larger areas of skin affected." (PMID 35418942, 2022). "However, the exact role of NPY in vitiligo pathogenesis is yet to be elucidated." (PMID 25221996, 2014).
vitiligo (continued). "In conclusion, our findings suggest that NPY exon 2 +1128 T/C, −399 T/C and IL1B −511 C/T promoter polymorphisms are significantly associated with vitiligo susceptibility, which might result in higher levels of IL1B thereby leading to autoimmune mediated responses in vitiligo." (PMID 25221996, 2014). "Thus, NPY might play a critical role in the pathogenesis of vitiligo, via neuro-immune mechanism on the melanocytes." (PMID 25221996, 2014). "Elevated neuropeptide levels, such as neuropeptide Y (NPY) and calcitonin gene-related peptide (CGRP), have been detected in the marginal areas of vitiligo lesions." (PMID 39958821, 2025). "In addition to the physiological expression pattern of NPY, several groups have shown that NPY is elevated in the affected skin and/or circulation of humans suffering from various skin pathologies, including atopic dermatitis, cutaneous melanoma, psoriasis, and vitiligo." (PMID 35418942, 2022). "Serum levels of NPY, MCH, ACTH, IFN-γ, CXCL10, IL-1β in patients with vitiligo of active (n = 10) and stable (n = 20) phases in both the intervention and control groups." (PMID 35721084, 2022). "Patients with vitiligo show increased levels of NPY and catecholamines, including dopamine, epinephrine, and norepinephrine." (PMID 40508132, 2025). "Moreover, the significant changes in the NPY, MCH, ACTH, IFN-γ, CXCL10 and IL-1β serum levels induced by camouflage and psychotherapy in the patients with vitiligo indicated the mechanism of psycho-neuro-endocrine-immuno-skin interaction." (PMID 35721084, 2022). "In addition, the study also emphasizes the influence of NPY and IL1B genes on disease progression for developing vitiligo." (PMID 25221996, 2014).
Abdominal obesity (9 papers, 2007 to 2025). Excessive fat around the stomach and abdomen. "The prolonged activation of the HPA axis with the attenuation of negative feedback in the HPA axis, which inhibits CRH and stimulates NPY expression, can be associated with abdominal obesity." (PMID 30717384, 2019). "However, its paralog (let-7b) had an inhibitory effect on NPY expression, which led to appetite suppression and a reduced risk of central obesity." (PMID 40217882, 2025). "TheY2R and increased levels of NPY in the adipose tissue mediated the accelerated fat accretion induced by chronic stress in adult male mice fed high fat diets, leading to abdominal obesity and metabolic-like syndrome." (PMID 22570731, 2012). "Leptin/NPY ratio and leptin/BMI ratio was also higher in the central obesity group and there was a more significant difference compared with controls." (PMID 17721641, 2007). "Therefore, NPY is released from sympathetic nerves in animals exposed to stressors, which in turn upregulates receptors in abdominal fat in a glucocorticoid-dependent manner, thereby increasing growth and developing abdominal obesity." (PMID 22612409, 2012).
cardiac hypertrophy (9 papers, 2016 to 2021). "NPY-I relieves all AAC-induced cardiac hypertrophy, confirming the cardio-protective property of NPY deficiency in CH." (PMID 33390770, 2021). "Therefore, the regulation of NPY deficiency may provide a new method for treating myocardial hypertrophy." (PMID 33390770, 2021). "Moreover, an NPY-Y2R polymorphism may interact and influence such an association, suggesting a potential role for the NPY system in the pathogenesis of ventricular hypertrophy." (PMID 27855650, 2016). "And more and more evidence shows that NPY can participate in the occurrence of myocardial hypertrophy through direct or indirect means." (PMID 34471416, 2021). "Although Npy was originally regarded as a neuropeptide, the role of NPY in inducing cardiac hypertrophy has been reported in recent studies." (PMID 34579143, 2021). "MiR-216b mimic and FoxO4 siRNA (small interfering RNA) inhibited NPY/Ang II-induced myocardial hypertrophy in vitro." (PMID 33390770, 2021). "After 28 days of intervention with YQHX and Meto, the level of NPY in tissue and serum decreased, which was beneficial to reduce the excessive innervation of the nervous system to the myocardial tissue and alleviate the progress of myocardial hypertrophy." (PMID 34471416, 2021). "To functionally analyze whether NPY1R/miR-216b/FoxO4 signal pathway is a necessary condition for NPY-induced cardiac hypertrophy, we transfected NPY into myocardial cells alone or in combination with BIBO3304 or miR-216b mimic or FoxO4 siRNA." (PMID 33390770, 2021). "NPY1R/miR-216b/FoxO4 pathway is critical for NPY induced cardiac hypertrophy." (PMID 33390770, 2021). "Long-term subcutaneous administration of NPY could induce cardiac dysfunction and cardiac hypertrophy in rats, and NPY treatment could also induce hypertrophy of cardiomyocytes in vitro." (PMID 31708788, 2019). "Previous studies in human patients and animal models of CHF have suggested that NPY may participate in the pathogenesis of myocardial hypertrophy and subsequent CHF." (PMID 27855650, 2016). "Based on the evidence presented above, we hypothesized that myocardial metabolic disturbance may be an early event before the morphological changes of myocardial hypertrophy, and changes in the NPY system may be involved." (PMID 27855650, 2016). "Moreover, pretreatment with TMZ may attenuate the metabolic disturbance of the myocardium before the morphological changes of ventricular hypertrophy can be detected, and these metabolic benefits of TMZ may involve the regulation of serum and myocardial NPY system." (PMID 27855650, 2016).
coronary artery disease (9 papers, 2013 to 2025). "NPY can promote cell proliferation, increasing the risk of coronary heart disease reinfarction and rebleeding." (PMID 33708805, 2021). "NPY can strongly contract the coronary arteries, thereby aggravating sympathetic nerve remodeling and causing or aggravating coronary artery disease." (PMID 34471416, 2021). "Previous clinical studies have suggested that NPY concentration is an independent predictor of coronary heart disease and ischemic stroke." (PMID 38087221, 2023). "A thorough study on the relationship between NPY and coronary heart disease may open the door for new treatments for the latter." (PMID 33708805, 2021). "Moreover, DPP4 protein has additional substrates that participate in responses to ischemic heart disease, such as stromal cell-derived factor-1 alpha (SDF1α), neuropeptide Y and substance P." (PMID 28587613, 2017). "Our findings suggest that NPY deletion may provide a new treatment for ischemic heart disease." (PMID 31708788, 2019). "Our study implies that NPY deletion may be a new treatment option for ischemic heart diseases." (PMID 31708788, 2019).
Ventricular arrhythmia (9 papers, 2018 to 2025). "Ventricular arrhythmias are associated with sympathoexcitation and increased co-transmitter neuropeptide Y (NPY) levels." (PMID 41052902, 2025). "A recent study revealed elevated cardiac NPY amounts in the acute phase of subarachnoid hemorrhage, with NPY acting on Y1 receptors to predispose to ventricular arrhythmias." (PMID 38803941, 2024). "Recent studies have reported that elevated neuropeptide Y and other sympathetic co-transmitters released from cardiac sympathetic neurons act on neuropeptide Y or other related receptors on the membrane of cardiac myocytes to cause the development of HF and ventricular arrhythmias." (PMID 36362099, 2022). "It had also been suggested that NPY was released when sympathetic nerve stimulation was a trigger for ventricular arrhythmia." (PMID 39107876, 2024). "Clinical data implicate NPY signaling in MI, progression of left ventricular dysfunction, ventricular arrhythmias and HF, thus we focused on characterizing neurons based on NPY expression." (PMID 37162194, 2023). "Recent studies show increased release of NPY in MI and HF, and elevated NPY is a predictor of post-MI ventricular arrhythmias." (PMID 35411324, 2022). "Interestingly, NPY triggers ventricular arrhythmias via the Y1 receptor in STEMI even after beta-blocker use." (PMID 38803941, 2024). "Moreover, NPY also increases the incidence of ventricular arrhythmias during experimental ST-elevation ischaemia reperfusion and this can also be prevented by a Y1 receptor antagonist." (PMID 31834357, 2020). "To directly assess whether NPY triggers ventricular arrhythmia, we assessed the incidence and severity of arrhythmia in the rat in the setting of ST-elevation ischaemia reperfusion." (PMID 31834357, 2020). "We also sought to ascertain whether patients undergoing PPCI for STEMI with high plasma NPY levels were therefore more likely to experience ventricular arrhythmias." (PMID 31834357, 2020). "We therefore hypothesized that despite maximal beta-blockade, NPY released during sympathetic stimulation can promote ventricular arrhythmias in a novel Langendorff perfused rat heart preparation with intact stellate ganglia and sympathetic innervation, and explore the underlying mechanisms." (PMID 31834357, 2020). "In patients presenting with STEMI treated with PPCI, NPY levels are associated with an increased incidence of ventricular arrhythmia in the immediate post-infarct period independent of classical risk factors such as late presentation, larger infarct size, and prior beta-blocker usage." (PMID 31834357, 2020). "However, in addition to the effect of NE there is evidence that NPY released during high level sympathetic stimulation may also increase rates of ventricular arrhythmia." (PMID 30283345, 2018). "In the OxAMI cohort, we therefore measured peripheral venous NPY levels immediately following PPCI and recorded ventricular arrhythmias during the first 48 h after reperfusion when 90% are known to occur." (PMID 31834357, 2020). "However, despite the lack of classical risk factors for ischaemia–reperfusion ventricular arrhythmias such as cardiogenic shock, late-presentation, larger infarct size, prior beta-blocker use, or longer pain to balloon time, patients with sustained VT/VF had significantly higher NPY levels." (PMID 31834357, 2020).